MICA (MHC class I polypeptide-related sequence A)
Diseases named in the same sentence as MICA in open-access papers (continued):
Sharing a sentence is not in itself a finding about the gene and the disease.
cancer (continued). "Some molecules associated with γδ T cell activation such as the Butyrophilin (BTN)-family, UL16 Binding Protein (ULBP)-family, MHC Class I Polypeptide-Related Sequence A (MICA) and B (MICB), Annexin A2 (ANXA2), and Apolipoprotein A1 (APOA1 were lower in cancer organoids." (PMID 38090581, 2023). "Moreover, the innate immune system response by NK cells to counter cancer cell tumors necessitates interaction between NKG2D receptors and MICA/B ligands." (PMID 35323710, 2022). "Furthermore, we measured the expression of well-known targets of DNA methylation in NK cell ligands in cancer cells, namely, MICA/B, during ECM detachment and observed low expression compared to ECM-attached cancer cells." (PMID 35323710, 2022). "Hence, spheroid cocultures are functionally relevant to the study of immunotherapies, echoing a recent study from Voest group, and pave the way for the study of anti-MICA/B and anti-NKG2A for cancer treatment." (PMID 30871626, 2019). "The stress proteins MICA and MICB are widely expressed by cancer cells due to genomic damage." (PMID 31234517, 2019). "Evidence has been reported that hypoxia is involved in the shedding and in the downregulation of major histocompatibility complex (MHC) class I polypeptide-related sequence A (MICA), a ligand for the activating NKG2D receptor expressed on the surface of cancer cells." (PMID 31540045, 2019). "Both ligands induced a downregulation of NKG2D expression and this is suggested to be an immune evasion mechanism performed by hrHPV to lead to cancer development, since the engagement of NKG2D and MICA/MICB plays an important role in cervical and other cancer immune surveillance." (PMID 29976244, 2018). "Although the intracellular mediators involved in the regulation of NKG2D ligands expression are still unknown, preliminary data would indicate that the MEK1/ERK, p38 MAPK, PI3K/Akt signaling pathways are involved in MICA and MICB up-regulation in cancer." (PMID 27563819, 2016). "A novel perspective in the regulation of MICA expression has been recently demonstrated by a study showing that up-regulation of MICA by genotoxic stress was enhanced by inhibiting STAT3 activity in both cancer and non-malignant cells." (PMID 24432022, 2014). "Similarly, elevated levels of the stress-inducible MHC class I chain-related surface glycoproteins, MICA and MICB, have been found to correlate with cancer stages and metastasis in several carcinomas." (PMID 21712991, 2011). "MICA is a functional ligand that stimulates the NKG2D receptor, and in addition to MICA, the interaction of MICB and ULBP, which are part of the human NKG2D ligand, with the NKG2D receptor is important for cancer cell recognition and NK cell-mediated cytotoxicity." (PMID 40045411, 2025). "Whether NKG2A and NKG2D, which likely have opposing functions with respect to T cell activation, are both concurrently functional is complex, given that the ligands of these receptors (i.e., HLA-E, and MICA/B, ULBP1-6, respectively) can be inducibly expressed in healthy and cancer tissue." (PMID 36796366, 2023). "In addition, the use of HDACi was reported to have the immunomodulatory effect on NKG2D system, and was able to reverse the RT-insensitive cancer cells with DNA damage-dependent NKG2D ligands, MICA/MICB-, to MICA/MICB+ cells as well as sensitize these cells for NK cell mediated cytotoxicity." (PMID 36185276, 2022). "However, there is a soluble form of MICA (sMICA) that decreases the expression and presentation of NKG2D, a natural cytotoxic receptor in natural killer cells, thus sMICA helps cancer cells to evade immune cell attack and contributing to a worse prognosis in cancer." (PMID 36338974, 2022). "Of note, also cancer stem cells (CSC), which represent a small radio-resistant population, were found not only to upregulate the Fas receptor in an irradiation dose-dependent manner but also to upregulate MICA/B, suggesting higher sensitization to NK cell killing." (PMID 33572396, 2021).
cancer (continued). "Vγ9 Vδ2 T cells can recognize phosphorylated antigens that accumulate in cancer cells, interact with the F1-ATPase expressed at the cancer cell surface, and recognize stress-induced molecules, such as the MHC class I chain-related molecules A and B (MICA and MICB), as well as UL16-binding proteins." (PMID 29316940, 2018). "Therefore, we compared the effects of Hsp90 inhibitor NVP-AUY922, HSF1 inhibitor NZ28 and HSF1 knockdown on the sensitivity of lung (H1339) and breast (MDA-MB-231, T47D) cancer cells to NK cell-mediated cytotoxicity and the expression of the NKG2D ligands MICA/B." (PMID 25854583, 2015). "Therefore, inhibition of MICA/B shedding may also promote CD8+ T‐cell‐driven immunity and enhance the therapeutic efficacy of T‐cell checkpoint blockers and serve as an alternative for cancer patients who are resistant to PD‐1/PD‐L1 antibodies." (PMID 38882209, 2024). "However, cancer cells shed NKG2D ligands through “a disintegrin and metalloproteinases” (ADAM) family, which could proteolytically cleave MICA resulting in a reduction of MICA surface density." (PMID 34439285, 2021). "Therefore, MICA expression had no influence on cancer survival in these cancer types." (PMID 29221214, 2017). "Regarding the mechanisms involved in driving NK dysregulation in solid pediatric cancers, we showed that these patients did not have raised plasma levels of soluble ULBP2 or soluble MICA, both of which inhibit NK cell function in some adult cancer patients." (PMID 39310750, 2024). "The current investigation quantitatively determined levels of CD56 and MICA expression in nonmalignant adult breast tissues with the hypothesis that lower levels of these markers would indicate suppressed NK cell immunoprotection in the breast epithelium and a higher incidence of cancer development." (PMID 29090365, 2018). "Some cancer cells lack or downregulate one or several MHC class I molecules and/or upregulate e.g. NKG2D ligands (NKG2DL) like the stress-inducible surface glycoproteins MHC class I-related chain A and B (MICA and MICB), and therefore provide no or not enough inhibitory stimulation." (PMID 27142426, 2016). "Therefore, the MICA sequence, and not MICA-STR, may have a prognostic value in this type of cancer." (PMID 33868281, 2021).
infection (66 papers, 2007 to 2025). The state of being infected such as from the introduction of a foreign agent such as serum, vaccine, antigenic substance or organism. "The membrane protein MICA generate response to various cellular stresses such as infection and oncogenic transformation, its mechanism of A5.1 allele association with disease risk of young OSCC remained unclear." (PMID 39830511, 2024). "MICA works in association with the MHC class I chain both in ex vivo infection and in patients with active HCMV infection." (PMID 37896804, 2023). "HLA-DRB, HLA-DQA1, and MICA genes have important roles in the adaptive immune response to infection—coding for MHC class I and II alleles, which are responsible for antigen processing and exogeneous peptide presentation." (PMID 33794208, 2021). "Here, the MICA variant associated with symptomatic infection is linked to higher MICA mRNA expression." (PMID 34650566, 2021). "As with all other NKG2D ligands, MICA expression in epithelial cells is induced by stress signals caused by infection." (PMID 33841421, 2021). "Here, the regulatory MICA variant associated with symptomatic infection is related to higher mRNA expression, possibly higher soluble MICA (sMICA), while the opposite is observed for all MICB variants (supplementary results)." (PMID 34650566, 2021). "The significance of MICA polymorphisms has been linked to a development of autoimmune conditions, cancer as well as pathogen infections." (PMID 32123296, 2020). "The Ad5 E3/19K gene not only downregulates HLA-1 during infection, but has also been demonstrated to directly cause retention of MICA and MICB in the ER, thus countering the immunogenic effects of the E1A gene and enabling immune evasion." (PMID 33352921, 2020). "MICA*A9 is a possible factor of innate immunity that could help explain the risk of infection and the different responses observed in SARS-CoV-2-infected individuals." (PMID 35805975, 2022). "The different MICA alleles may vary in the activation of these cells and produce different degrees of activation and control of the infection." (PMID 35805975, 2022). "Reduction of MICA expression could be an important cause or contributing factor for CDI and restoration of MICA expression in the gut could be a treatment strategy for infection." (PMID 33841421, 2021). "Flow cytometry analysis revealed that Bacilli infection led to a 62% reduction in mean fluorescence intensity (MFI) of the NKG2D ligand MICA/B and a 47% decrease in ULBP1/2 expression on the surface of Huh7 cells." (PMID 40693141, 2025). "Conversely, at 24 hours after infection, only AM from resisters displayed an upregulation of MHC class I polypeptide–related sequence A (MICA) transcripts, which encode an activating ligand for poly-CTL." (PMID 39836471, 2025). "MICA and MICB variants were previously associated with SARS-CoV-2 infection, especially with symptomatic infections." (PMID 41153412, 2025). "At 24 hours after infection, the stress-induced MICA gene was more strongly upregulated in resister AM in response to Mtb than LTBI AM." (PMID 39836471, 2025). "We observed a downregulation in MICA at 36 hrs post-infection, with a decreasing trend at the following time points." (PMID 37753084, 2023). "Genes and alleles controlling the immune response such as MICA and their HLA ligands (MICA-HLA: MICA*002~HLA-B*35), and KIR (KIR: KIR3DS1-Bw4-80Ile; KIR2DS1+/C2++ KIR3DS1+/Bw4-80Ile+) increase the risk of infection." (PMID 34222043, 2021). "Also, a differential regulation of cell surface expression of MICA isoforms has been observed upon infection with cytomegalovirus, suggesting that resistance to infectious agents could be a driving force for the selection of several MICA alleles in the population." (PMID 34394116, 2021). "Among the genes related to immune modulation, we detected variants in MICA and MICB associated with symptomatic infections." (PMID 34650566, 2021).
infection (continued). "Similar results were also obtained in western blot analysis, demonstrating a redistribution of MICA*008 to a ‘smear’ of high molecular weight forms upon BAC20 ΔUS9 infection." (PMID 33939764, 2021). "We assessed MICA*008 surface expression in uninfected (UI) and infected cells at 72 h post infection (hpi)." (PMID 33824318, 2021). "We demonstrate that the infected cells respond to the infection and that, upon infection, the mRNA and the total protein amount of MICA, MICB, ULBP2, and ULBP3 are upregulated." (PMID 32698530, 2020). "Both ULBP2 and MICA surface expression levels were found to be decreased following infection with HSV-1 strain F. Concurrent with a loss of surface expression, MICA messenger RNA (mRNA) levels were decreased." (PMID 28443092, 2017). "Recently it was shown that the expression of MHC class I-related chain A (MICA) was highly elevated after 27 days of infection in human hepatocytes, suggesting that they can act as APCs." (PMID 28218682, 2017). "Infection with this mutant also resulted in a very marked increase in the total cellular abundance of MICA/B." (PMID 24787765, 2014). "In agreement with this, we found that both VSV10 and VSVΔM51 infection decrease the intracellular protein level of MICA/B after FR901228 treatment." (PMID 21857986, 2011). "A strong increase in the MICA mRNA level was observed after VSVΔM51 infection and as expected combined VSVΔM51 infection and FR901228 treatment led to a further increase in MICA mRNA expression (data not shown)." (PMID 21857986, 2011). "Furthermore, the expression of MICA/B on CD4+ T cells generally increased with the duration of infection, with a more pronounced elevation observed in the IR group." (PMID 40061947, 2025). "The combined stronger induction of MICA in AM with the higher number of NKG2D-expressing poly-CTLs in resister alveoli provided a strong case that cytotoxic mechanisms are a main effector of increased resistance to infection with Mtb." (PMID 39836471, 2025). "Hepatocytes express stress-induced ligands like MHC class I-related chain A/B (MICA/B) under damage, infection, or oncogenic stress, which are recognized by γδT cell NKG2D receptors, triggering cytotoxic responses via perforin and granzyme, and pro-inflammatory cytokine release (e.g., IFN-γ, TNF-α)." (PMID 40141420, 2025). "Moreover, MICA and MICB, ligands for NKG2D, are induced upon cellular stress during pathogenic infection and NKG2D on decidual NK cells is involved in cytotoxic killing of virus-infected decidual fibroblasts." (PMID 38571943, 2024). "Our results indicate that the MICA*A9 allele is related to infection as well as to symptomatic disease but not to severe disease." (PMID 35805975, 2022). "Whether this signifies the effect of additional MICA*008-sequestering factor(s) or merely reflects changes in MICA*008 production and maturation rates during infection remains unknown." (PMID 33939764, 2021). "In contrast, when we infected FLS1 HFFs (endogenous full-length MICA), there were no discernible differences between BAC2 and BAC2 ΔUL147A infected cells in MICA surface expression or in total MICA levels, confirming UL147A’s allele specificity also during infection." (PMID 33939764, 2021). "At 96 hours post-infection (hpi), MICA*008 surface expression was assayed by flow cytometry." (PMID 33939764, 2021). "However, MICA expression is triggered under pathologic circumstances comprising cellular stress, tumorigenesis or pathogen infection." (PMID 32123296, 2020). "Further, infection with HBV/HCV can cause up-regulation of matrix metalloproteins, high levels of which lead to increased production of sMICA and decreased membrane-bound MICA tumor antigen protein." (PMID 31419949, 2019). "First, MV-Edm infection compelled HCC cells to express the specific NKG2D ligands MICA/B, which may contribute to the activation of CD8+NKG2D+ cells." (PMID 28701757, 2017). "We found that MV-Edm infection significantly upregulated MICA/B in HCC cells." (PMID 28701757, 2017).
infection (continued). "Similarly, MICA maturation was unimpeded upon infection with ΔRh159 consistent with the increased MICA surface expression compared to RhCMV." (PMID 27580123, 2016). "In this context, MicA and RybB may facilitate rapid down regulation of OM proteins in the initial phase of infection, only to enable omp expression when required again during the later IBC stage." (PMID 26291711, 2015). "Thus, NKG2D recognizes the stress-induced ligand MHC class I polypeptide-related sequence A (MICA), while NKp46 and NKp44 can directly bind influenza hemagglutinin, a response that is key to the role of NK cells in protecting against infection by the virus." (PMID 23801996, 2013). "Unexpectedly, VSVΔM51 infection did only result in a minor level of MICA/B surface expression." (PMID 21857986, 2011). "Interestingly, VSV10 infection leads to a robust induction of MICA mRNA expression, to a level resembling the induction by HDAC-inhibitor, FR901228, which is a well-known inducer of NKG2D-ligand expression." (PMID 21857986, 2011). "An up-regulation of MICA mRNA expression in Jurkat T-cells could be observed 4 hr post treatment with FR901228, whereas an up-regulation of MICA mRNA following VSV10 infection was observed after 12 hr." (PMID 21857986, 2011). "The data suggested that the MICA locus might modify host inflammatory response to Ct infection." (PMID 27559544, 2016). "Moreover, the increase of NKG2D expression may help to protect the fetus against pathogenic infections, since the NKG2D ligands, MICA/B and ULBP1-5, are mainly induced by cellular stresses such as cell damage or pathogen infection." (PMID 22242197, 2012). "Based on these findings, we conclude recognition of cell surface MICA by CD8+ effector T cells via NKG2D could constitute critical co-stimulatory signal that complement the antigenic peptide/MHC-induced TCR activation at the site of infection." (PMID 20844584, 2010). "NKG2 receptors, including NKG2A, NKG2C, and NKG2D, are C-type lectin-like receptors that bind to HLA-E or stress-induced ligands like MICA/MICB, modulating NK cell activation in response to infection or malignancy." (PMID 41153412, 2025). "MICA and MICB genes were transcribed by macrophages with higher expression at the 24 hours after infection time point." (PMID 39836471, 2025). "Infection with the ΔcagA and ΔcagL mutants resulted in only slightly lower levels of MICA and MICB mRNA expression, whereas infection with the ΔvacA mutant resulted in greatly lower levels of MICA and MICB mRNA expression, compared to infection with the WT." (PMID 38318189, 2024). "Using cell-culture based infection models, we found that H. pylori infection of stomach epithelial cells induced both gene expression and soluble release of the NKG2D-Ls MICA and MICB and reduced MICA/B cell surface expression." (PMID 38318189, 2024). "MICA and MICB are Class I MHC-related glycoproteins that are upregulated on the surface of cells in response to stress, for instance due to infection or malignant transformation." (PMID 38550583, 2024). "Next, we evaluated the expression levels of the NKG2D ligands MICA, MICB and ULBP1-3 at 48 hrs post-infection." (PMID 37753084, 2023). "Twenty-four hours following infection, we stained the mock-infected and the infected cells for the expression of NKG2D ligands: MICA, MICB, ULBP1, ULBP2, ULBP3, and ULBP4." (PMID 32698530, 2020). "Whereas 64% of mock-infected A673 cells expressed MICA/MICB (mock infection), 51% of A673 cells expressed MICA/MICB after MeV-GFP infection at 48 hpi (infection with MeV-GFP)." (PMID 31795974, 2019). "Hepatitis B virus (HBV) releases HBc and HBx proteins to promote the expression of transcription factors GATA-2 and GATA-3 after infection, and GATA-2 and GATA-3 specifically inhibit MICA/B expression by directly binding to the promoter region of MICA/B." (PMID 30813924, 2019).